BCR (BCR activator of RhoGEF and GTPase)
Diseases named in the same sentence as BCR in open-access papers (continued):
Sharing a sentence is not in itself a finding about the gene and the disease.
tumor (continued). "For example, the inhibition of tyrosine kinase receptor signaling by CD117 will effectively inhibit mast cell recruitment; the inhibition of breakpoint cluster region (BCR)/ABL and protein kinase C (PKC) signaling has also demonstrated the clearance of mast cells and tumor suppression." (PMID 37055849, 2023). "A recent study showed targeting DDR1 as a therapeutic strategy against resistance to BRAF and MEK inhibitors, further confirming the significance of our findings, which suggest an unprecedented role of the interactome of DDR1, BCR, and ABL1 proteins with EGFR-ERBB2-4 signaling in tumor progression." (PMID 35664781, 2022). "Furthermore, we calculated immune cell infiltration, immune checkpoint, the T-cell receptor/B-cell receptor (TCR/BCR), SNV, and Tumor Immune Dysfunction and Exclusion (TIDE) scores in TCGA database." (PMID 35860590, 2022). "We found inhibition of DDR1/BCR signaling with EGFR/ERBB2 to be effective independent of KRAS mutation type and status in COAD and additional primary tumor model of GBM." (PMID 35664781, 2022). "Downregulated genes include: 1) Immune system activators, such as CD86; 2) blood tumor suppressors ID2 and KLF4; 3) CEBPB, CEBPB is a BCR/ABL negative regulator gene, which can inhibit the proliferation of BCR/ABL-positive cells, and promote cell differentiation." (PMID 36699453, 2022). "This speculation is partly supported by the association between the inter-score and the immune-related features other than TMB/PD-L1 (e.g., BCR/TCR diversity, mRNA expression of immune checkpoints, and quantity of tumor-infiltrating immune cells)." (PMID 35042953, 2022). "Sca1-ETV6-RUNX1 + Kdm5cf/wt + Sca1-Cre B-ALLs displayed clonal immature BCR rearrangement, and FACS analysis revealed a CD19+B220+IgM– cell surface phenotype of the tumor cells in BM, PB, and spleen with the capability to infiltrate other tissues like the spleen, liver, and small intestine." (PMID 34336858, 2021). "Our single‐cell analyses provide a new perspective for the relationship, as we profiled the BCR in both tumor and nontumor regions for CRC patients." (PMID 33463049, 2021). "This dataset derived from radically resected tumours demonstrated that PTENLOW (P = 0.0014), CXCR1HIGH (P = 0.017) and CXCR2HIGH (P = 0.035) expression each independently correlated with accelerated biochemical recurrence (BCR)." (PMID 32743555, 2020). "However, except for patients 3 and 9, other SCCE samples showed less leucocyte infiltration, BCR/TCR diversity and lower expression of immune‐stimulatory factors in tumor tissues, presenting immunological ignorance." (PMID 33033616, 2020). "Third, due to a lack of eligible data, subgroup analyses for BCR-FS based on tumor stage and various therapies were not be performed." (PMID 33318295, 2020). "In myeloid leukemia where β-arr mediates the initiation and maintenance of tumor cells, the interaction of β-arr1 with the DNA-binding Enhancer of Zeste Homologue 2 (EZH2) protein mediates BCR/ABL histone acetylation during tumor progression." (PMID 30837880, 2019). "On univariate Cox regression analysis laterality did not significantly predict shorter time to BCR by index tumor extent (HR 0.571, 95% CI 0.240 – 1.357, p = 205)." (PMID 30648826, 2019). "Therefore, characterizing tumor TCR and BCR repertoires, particularly the CDR3s, is critical to understanding antigen recognition and tumor–immune interactions." (PMID 31771646, 2019). "As we detected minor BCR-specific subclones in primary TCL1 tumors, we first wanted to analyze clonal dynamics of B cell receptor usage of the individual tumors upon serial transplantation of tumor cells into WT recipients." (PMID 30262843, 2019). "The fact that CML arises in mice under these circumstances indicates that the absence of BCR-ABL expression is not required for the generation of differentiated tumor cells." (PMID 29772764, 2018).
tumor (continued). "Besides the BCR pathway, JAK-STAT represents another important tumor-promoting signaling pathway in the pathogenesis of CLL." (PMID 28088788, 2017). "In addition, tumor recognition depends on lymphocyte activation and clonal expansion, which is initiated by TCR and BCR recognition." (PMID 28881849, 2017). "Therefore, miR-138, by the advantage of a BCR-ABL/GATA1/miR-138 integrated circuitry, acts as a tumor suppressor miRNA involved in the pathogenesis of CML and its clinical response to imatinib." (PMID 26967056, 2016). "Importantly, in comparing the exposure of K562 single tumor cell to DOX alone or plus BORT formulations, the combined Tf-L-BORT and DOX resulted in the most downregulation of BCR/ABL and Sp1." (PMID 27144331, 2016). "Furthermore, L-BORT exposure significantly blocked BCR/ABL kinase activities and sensitized CML cell lines, tumor cells and doxorubicin (DOX) resistant cells to DOX." (PMID 27144331, 2016). "In the context of the finding that imatinib selects for survival of clones with low-level deregulated BCR-ABL [16•], we suggested that potent and durable suppression of deregulated BCR-ABL activity is an important mechanism of tumor suppression by inhibiting oncogenic addiction." (PMID 24500518, 2014). "We show here that in BCR/ABL+ tumors the absence of STAT3 accelerates tumor growth assigning a tumor suppressing function to STAT3 in this disease." (PMID 24473086, 2014). "On side of the tumor, a direct control of the expression of the NKG2D ligands (NKG2DLs) MHC class I-related chain molecules (MIC)A/B by BCR/ABL has been shown and was reduced by different TKIs leading to decreased NK cell-mediated cytotoxicity and IFN-γ production." (PMID 23316191, 2012). "Our finding is consistent with a previous study which shows that IRF4 functions as tumor suppressor in BCR/ABL oncogene induced B-ALL and further demonstrates that IRF4 is capable of functioning as a tumor suppressor against a broad spectrum of oncogene insults at the pre-B stage." (PMID 21818355, 2011). "Although the mechanisms responsible for CML disease progression are still largely unclear, growing evidence suggests that the phenotype of CML-BC cells depends on the unrestrained activity of BCR/ABL and on the genetic or functional inactivation of genes with tumour suppressor activity." (PMID 16953242, 2006). "Interestingly, COSMIC fusion BCR::ABL1 was not tumor enriched in our analysis, likely due to paucity of the relevant tumors in TCGA." (PMID 37323575, 2023). "Interestingly, and in sharp contrast to KMT2A-r models, BCL-2+BCR::ABL1 mutated samples did not respond to VEN application, with similar blast kinetics and tumor cell frequencies in controls and treated animals." (PMID 35778418, 2022). "It has been shown that many ALL carry non-productive BCR/TCR in both alleles or the only expressed dominant allele, which was suggested to support the hypothesis that BCR might act as a tumor suppressor in most cases of B-precursor ALL." (PMID 35712632, 2022). "We further investigated the tumor antigen presentation capacity of the three phenotypes, and observed that TIME-3 had the highest APS and MHC-related molecules expression level, as opposed to TIME-1 (all, P < 0.01), which was consistent with the CYT value and BCR/TCR diversity (all, P < 0.05)." (PMID 33407585, 2021). "BCR analysis of CLL tumors as well as transplanted tumors in recipient mice revealed no clonal shifts upon tumor transfer in any mouse genotype, except for one transplanted OT1 mouse (ID 423), in which the clonal composition changed, with a previously minor clone expanding." (PMID 34206229, 2021). "Interestingly, viability of HAP1 cells did not seem to be affected by the knockout of known tumor type-specific oncogenes such as BCR, PIK3CA, KRAS, CTNNB1, or BRAF." (PMID 33228647, 2020).
tumor (continued). "As BCR-ABL transcript is solely expressed by the leukemic cells, its measurement by mean of quantitative PCR (Q-PCR) is considered one of the most sensitive and specific techniques to indirectly assess the tumor burden, and is the standard de facto for monitoring minimal residual disease in CML." (PMID 32548108, 2020). "In this study, we characterized TCR and BCR repertoires in both pediatric and adult AML by detecting and analyzing the CDR3 sequences in TCR α, β, γ, and δ chains and B cell immunoglobulin (Ig) heavy (IgH) and light (IgL, IgK) chains from the RNA-seq data in AML patients and non-tumor donors." (PMID 31771646, 2019). "Furthermore, the levels of BCR/ABL protein, phospho-BCR/ABL and downstream molecules were significantly lower in co-treated tumor than in tumors treated with JNJ-165 or PD180970, which may contribute to combination therapy cytotoxicity." (PMID 27999193, 2017). "Here, we present in vivo evidence, that the combined absence of Aid and Rag1 in tumor prone murine pro-B cells accelerates pro-B ALL incidence, which suggests a functional role of Aid in Rag1 deficient BM pro-B-cells even before the expression of a pre-BCR." (PMID 29100269, 2017). "The underlying mechanisms of imatinib resistance could be a result of point mutations in the breakpoint cluster region-Abelson murine leukemia (BCR-ABL) kinase domain, amplification of the BCR-ABL gene, and overexpression of the multidrug resistance protein 1 (MRP1) gene in tumor cells." (PMID 28969100, 2017). "Thus, a prominent reduction of miR-29b in CML might implicate miR-29b as a potential tumor suppressor in CML by targeting ABL1 and BCR/ABL1." (PMID 26967056, 2016). "Ex vivo analysis performed on tumor cells did not reveal any difference in BCR-ABL expression between K562S and K562DOX, excluding the possibility that the relapse might be due to an increased expression of the oncogenic protein." (PMID 26149173, 2015). "Additionally, several immune characteristics, including aneuploidy score, HRD score, BCR richness, TCR richness, non-silent mutation rate and segment number were compared between the subtypes, revealing the tumor immunosuppressive microenvironment (TIME) of PMRS-high patients." (PMID 40084259, 2025). "Firstly, while our trajectory and scTCR/BCR-seq sharing analyses support the intra-tumoral differentiation of CD8+ and CD4+ T cells as well as B cells in mTLS, the origin of the T and B cells, whether already in the site of tumor or from the organ, such as tdLNs or blood, is unclear." (PMID 40335494, 2025). "In addition, we also found that the MYC signaling activation group also showed higher intratumoral heterogeneity, IFN-gamma response and M1/M2 macrophages and lower TCR shannon, while the tumor purity and BCR shannon did not be significantly different between the two groups." (PMID 36299592, 2022). "To determine whether tumor‐infiltrating B cells of the high HER2‐AAb group responded to specific TAAs including HER2, we examined the mRNA sequence of the CDR3 region of the IgHV and IgHJ genes by the unbiased amplification of BCR genes followed by next‐generation sequencing." (PMID 33506656, 2021). "While no overall changes of BCR and TCR diversities were found, tumor samples from patients treated with RUX + PAC run-in therapy showed significantly decreased BCR but not TCR diversity." (PMID 38297352, 2024). "NILO only had minor effects on BCR::ABL1− cell lines, but did not inhibit tumor cell lysis of BCR::ABL1+ cell lines." (PMID 35551463, 2022). "Four tumor samples (patients 3, 5, 6 (without matching NAT) and 9) exhibited higher diversity and clonality of BCR, along with higher maximum counts of their BCR clone types." (PMID 33033616, 2020).
tumor (continued). "We demonstrate that the N-end rule–based PROTACs with distinct amino acids (Arg, Lys, Leu, and Phe) easily provide a range of BCR–ABL concentration under the same condition, and the Arg-PEG1-Dasa can effectively suppress BCR–ABL–induced tumor growth without overt drug toxicity in vivo." (PMID 37392851, 2023). "However, a single BCR-ABL copy expressed from endogenous BCR locus, enhanced bone marrow grafting capacity without inducing any neoplasm." (PMID 35006395, 2021).
cancer (242 papers, 2002 to 2026). A tumor composed of atypical neoplastic, often pleomorphic cells that invade other tissues. "Approximately 85% to 100% of the patients in BC with BCR::ABL1 kinase domain mutations also had cancer gene mutations, including gene fusions and deletions." (PMID 37762109, 2023). "NGS studies have confirmed the role of mutations in cancer-related genes other than BCR::ABL1 mutations in drug resistance and treatment failure." (PMID 37762109, 2023). "In blast crisis, 85% to 100% of patients with BCR::ABL1 kinase domain mutations also had cancer gene mutations, including gene fusions and deletions." (PMID 35158889, 2022). "For single cancer cell surface protein expressions such as human epidermal growth factor receptor 2 (HER2) or single cancer gene mutations such as BCR-ABL fusion, there are clear diagnostics and therapeutic guidelines for care." (PMID 33499867, 2021). "B-lymphoblastic lymphoma (B-LBL) with BCR/ABL mutation (Ph+ B-LBL) is a rare type of cancer in both childhood and adults." (PMID 34115047, 2021). "In summary, our data show that the combination of avasimibe and imatinib synergistically suppresses BCR-ABL mutation-independent imatinib-resistant CML proliferation by targeting cancer-specific CE accumulation, MAPK, and native BCR-ABL signaling." (PMID 28719608, 2017). "Imatinib is a tyrosine kinase specific inhibitor specifically designed to fit the BCR-Abl ATP-binding site of the protein created by the BCR-Abl translocation enabling for the first time specific cancer therapy by targeting a causal molecular target." (PMID 26330891, 2015). "When we characterized the function of the 34 prostate genes, we found they were significantly associated with BCR free survival and to multiple cancer pathway genes." (PMID 24397863, 2014). "The impact of cancer-related gene mutations detected at the time of CML diagnosis may vary depending on whether they were acquired before or after BCR::ABL1." (PMID 35932396, 2022). "Mutations in cancer-associated genes adversely affect outcome and their detection at diagnosis may guide therapeutic choice and offer non-BCR::ABL1 targeted therapies." (PMID 35932396, 2022). "However, an indirect evidence connects its oncogenic BCR-fused variant (BCR/Abl) to the promotion of podosome formation in leukaemic cancer cells." (PMID 19531213, 2009). "However, lymphoid gene mutations may also be relevant for lymphoid phenotype BC CML, and BCR::ABL1 mutations frequently co-occur with cancer gene mutations." (PMID 37762109, 2023). "However, lymphoid gene mutations may also be relevant for lymphoid phenotype blast crisis CML and BCR::ABL1 mutations frequently co-occur with mutated cancer genes." (PMID 35158889, 2022). "Therefore, shuttling appears to be a perfect target in those scenarios where the inhibition of BCR-ABL is insufficient to promote eradication of the cancer: in the presence of BCR-ABL mutations that impair sensitivity to TKI, in the stem cell pool and in CML blast crisis/Ph+ ALL." (PMID 31614958, 2019). "To date, only about two‐thirds of the kinome has been covered, and more substantial inferences could be made with further population of resources (such as PhosphoSitePlus), especially when the latter also cover cancer‐associated aberrations such as fusion gene products BCR‐ABL and EML4‐ALK." (PMID 30979792, 2019). "The high-quality fluorescence imaging of MDA-MB-231 cancer cells was also obtained in vitro using BCR-NLPs." (PMID 42211385, 2026). "In this study, we examined the expression of ABL-E255V in human cancer cells transduced with ABL-minigene-E255V, as well as mutated CML cells carrying the E255V mutation in the BCR-ABL gene." (PMID 39931057, 2025). "In our exploration of the N-end rule–based PROTACs for PD treatment, we have selected the amino acid Arg as the degradation signal, which was previously employed in the PROTACs against various cancer drivers (e. g., ERRα, BCR-ABL, etc.)." (PMID 40615042, 2025).
cancer (continued). "Our estimates of the duration from the start of BCR::ABL1 clonal expansion to disease presentation fall within ranges from radiobiological studies of cancer incidences in Japanese survivors of the atomic bombs." (PMID 40205062, 2025). "Cancers driven by a single acquired genetic alteration are rare and we did not identify concurrent genomic alterations required for clonal expansion beyond BCR::ABL1." (PMID 40205062, 2025). "TCR and BCR repertoire analysis can identify T‐cell or B‐cell clones specific for pathogens or cancer cells." (PMID 40785616, 2025). "Mechanistically, SP140 mutations caused downregulation of BCR signaling and MYC targets, leading to cancer progression and poor prognosis." (PMID 41188771, 2025). "This is the first study to explore the best prediction model of QTc prolongation based on routine EMR data by applying conventional statistical LR with ML modeling for cancer patients newly treated with the commonly used oral VEGFis and BCR-ABLis." (PMID 40817221, 2025). "It was identified that the compound SIAIS562055 sustainably degraded SOS1 levels and inhibit downstream effectors, exhibiting potent antitumor activity in both KRAS-mutant cancers and BCR–ABL+ CML." (PMID 39437162, 2025). "In summary, these experiments showed that RoCK and ROI can be used both in cell lines and patient samples for the detection of both major and minor BCR::ABL1 fusion transcripts in the context of cancer." (PMID 41372142, 2025). "First, the correlation between ZDHHC9 expression and genomic features, along with immune-related indicators—including mutations, neoantigens, CTA (cancer testis antigens), and TCR/BCR diversity—was assessed." (PMID 40740766, 2025). "There are four populations of monocolonal isogenic Ba/F3 murine cell lines, two transformed with the BCR-ABL fusion oncogene and two made resistant to the cancer growth blocker imatinib by the BCR-ABL-T3151 mutation." (PMID 40410271, 2025). "Here, we engineered monobodies targeting the BCR::ABL1 tyrosine kinase for efficient delivery by the T3SS, quantified cytosolic delivery and target engagement in cancer cells and monitored inhibition of BCR::ABL1 signaling." (PMID 39415233, 2024). "For example, imatinib has transformed CML from a fatal cancer to a chronic disease, by specifically targeting the BCR–ABL fusion protein that drives the proliferation of leukemic cells." (PMID 39184861, 2024). "Although the systemic use of CD45 inhibitors in the clinic would abrogate TCR and BCR signaling, both of which are required for an effective anti‐cancer immune response, this study identifies a potential clinical application in adoptive immunotherapy." (PMID 37855066, 2024). "Combination therapies targeting ILK and ABL’s oncogenic counterpart BCR-ABL are preferred for other cancers like leukemia when anti-ABL monotherapies are ineffective." (PMID 37508338, 2023). "When ABL’s oncogenic counterpart BCR-ABL localizes to the cytosol, proliferation increases and increased cytosolic ABL has been associated with more aggressive cancers." (PMID 37508338, 2023). "The oncogenic kinasesyielded a substantially different linear motif when compared to ABL1.Kinase set enrichment analysis with human pY-sites that have highlinear motif scores well-recalled BCR-ABL driven cancer cell linesfrom human phospho-proteome data sets." (PMID 37053475, 2023). "In parallel to plasma cell differentiation, memory cell infiltrate in these patients was more skewed towards a class-switched or germinal centre phenotype with lower degrees of BCR clonality in smokers and advanced-stage cancers." (PMID 37398676, 2023). "Regardless of the mechanism, several recent studies have shown that ILK downregulation or inhibition sensitizes cancer cells to various chemotherapeutics that target ABL or BCR-ABL." (PMID 37508338, 2023).